GRIA4 (glutamate ionotropic receptor AMPA type subunit 4)
Description:
Ionotropic glutamate receptor that functions as a ligand-gated cation channel, gated by L-glutamate and glutamatergic agonists such as alpha-amino-3-hydroxy-5-methyl-4-isoxazolepropionic acid (AMPA), quisqualic acid, and kainic acid (By similarity). L-glutamate acts as an excitatory neurotransmitter at many synapses in the central nervous system and plays an important role in fast excitatory synaptic transmission (By similarity). Binding of the excitatory neurotransmitter L-glutamate induces a conformation change, leading to the opening of the cation channel, and thereby converts the chemical signal to an electrical impulse upon entry of monovalent and divalent cations such as sodium and calcium. The receptor then desensitizes rapidly and enters a transient inactive state, characterized by the presence of bound agonist (By similarity). In the presence of CACNG8, shows resensitization which is characterized by a delayed accumulation of current flux upon continued application of L-glutamate.
Synonyms: GluR-4; GluR4; GluA4; GLURD; GluR-D; GLUR4C; GluA4-ATD; NEDSGA
Tractability: Small molecule: an approved drug acts on it; a high-quality ligand is known; it belongs to a druggable protein family. Antibody: its Gene Ontology location is reachable by antibodies, with high confidence; UniProt places it where antibodies can reach, with medium confidence; UniProt predicts a signal peptide or a membrane-spanning region. PROTAC: ubiquitination databases record sites on it; its protein half-life has been measured; a small molecule that binds it is known.
Target class: Ligand-gated ion channel; Ionotropic glutamate receptor; AMPA receptor; Ion channel
Gene: Protein-coding gene on chromosome 11 (105,609,535 to 105,982,090, forward strand). Ensembl gene ENSG00000152578.
Subcellular location: Cell membrane; Postsynaptic cell membrane; Cell projection, dendrite
Subcellular location (Human Protein Atlas): Focal adhesion sites
Pathways (Reactome):
Neuronal System: Activation of AMPA receptors; Synaptic adhesion-like molecules; Trafficking of AMPA receptors; Trafficking of GluR2-containing AMPA receptors; Unblocking of NMDA receptors, glutamate binding and activation
Gene Ontology:
Molecular function: AMPA glutamate receptor activity; ligand-gated monoatomic ion channel activity involved in regulation of presynaptic membrane potential; amyloid-beta binding; glutamate-gated receptor activity; transmitter-gated monoatomic ion channel activity involved in regulation of postsynaptic membrane potential; ligand-gated monoatomic ion channel activity; monoatomic ion channel activity; signaling receptor activity
Biological process: negative regulation of smooth muscle cell apoptotic process; glutamate receptor signaling pathway; modulation of chemical synaptic transmission; synaptic transmission, glutamatergic; ionotropic glutamate receptor signaling pathway; monoatomic ion transmembrane transport; monoatomic ion transport; regulation of postsynaptic membrane potential; regulation of presynaptic membrane potential
Cellular component: extracellular vesicle; AMPA glutamate receptor complex; dendrite; dendritic spine; endocytic vesicle membrane; neuronal cell body; plasma membrane; postsynaptic density membrane; postsynaptic membrane; membrane
Genetic constraint (gnomAD): Loss-of-function variants: 9 observed, 38.08 expected, observed/expected ratio (o/e) 0.24, 90% interval 0.14 to 0.41. The upper end of that interval is the gene's LOEUF score, 0.41, which puts it in group 1 of 6, group 1 being the genes least tolerant of losing a copy. Missense variants: 343 observed, 543.76 expected, observed/expected ratio (o/e) 0.63, 90% interval 0.58 to 0.69. Synonymous variants: 192 observed, 203.43 expected, observed/expected ratio (o/e) 0.94, 90% interval 0.84 to 1.06.
Gene-disease validity (ClinGen):
ClinGen rates the evidence that GRIA4 causes each of these diseases.
neurodevelopmental disorder with or without seizures and gait abnormalities (autosomal dominant): Moderate.
Homologues: Orthologues: rat Gria4 (99% identical), dog GRIA4 (99% identical), rabbit GRIA4 (99% identical), chimpanzee GRIA4 (99% identical), mouse Gria4 (99% identical), pig GRIA4 (94% identical), macaque GRIA4 (93% identical), guinea pig GRIA4 (90% identical), zebrafish gria4a (89% identical), zebrafish gria4b (89% identical), tropical clawed frog gria4 (87% identical), Drosophila melanogaster GluRIB (45% identical), and 38 more. Paralogues in human: GRIA3 (72% identical), GRIA2 (70% identical), GRIA1 (68% identical), GRIK1 (38% identical), GRIK2 (37% identical), GRIK3 (36% identical), GRIK4 (34% identical), GRIK5 (34% identical), GRID1 (28% identical), GRID2 (26% identical), GRIN1 (25% identical), GRIN2C (22% identical), and 5 more.
Diseases named in the same sentence as GRIA4 in open-access papers:
GRIA4 is named in the same sentence as 69 diseases in open-access papers, as found by Europe PMC text mining. Sharing a sentence is not in itself a finding about the gene and the disease. The quoted sentences say what the papers report.
schizophrenia (13 papers, 2011 to 2025). A major psychotic disorder characterized by abnormalities in the perception or expression of reality. "Mutations in GRIA4 have been implicated in schizophrenia and intellectual disability, underscoring the importance of this AMPAR subunit for synaptic function." (PMID 31685637, 2019). "NPTX2 binds to α-amino-3-hydroxy-5-methyl-4-isoxazolepropionic acid (AMPA) receptor subunit Glutamate receptor 4 (GRIA4) in neuronal tissues and has a presynaptic role in Pyramidal neurons with loss/loss of function associated with Alzheimer’s disease and Schizophrenia." (PMID 38875182, 2024). "Variants in the Gria4 gene are linked to schizophrenia and intellectual disability." (PMID 32467583, 2020). "Moreover, GRIA4-deficient mice exhibit schizophrenia-related phenotypes." (PMID 25206360, 2014). "Examples of diagnostic-biased genes include GRIA4 (glutamate receptor, inotropic, AMPA4) and ASTN2 (astrotactin 2), both of these genes have been previously implicated in schizophrenia." (PMID 25206360, 2014). "For example, genetic variations in GRIA4, a subunit of AMPA receptor that mediates fast synaptic excitatory neurotransmission, have been associated with schizophrenia and antipsychotic responses in patients." (PMID 25206360, 2014). "We identified a number of genes with significant epigenetic alterations in schizophrenia, and some of these genes, such as GRIA4, ASTN2, and DCDC2 (doublecortin domain containing 2) with increased DNA methylation at particular CpG loci, have previously been implicated in schizophrenia." (PMID 25206360, 2014). "The molecules that mostly contributed to discriminate schizophrenia from controls were EAAT2, CAMK2A, Synapsin-1, l-Asn, GRIA2, GRIA4, and SLC17A7 whereas the ones that barely contributed to the discrimination were: Gly, mGluR5, CaMKIIα, VGluT1, and d-Asp." (PMID 35217646, 2022).
Intellectual disability (6 papers, 2019 to 2025). "Pathogenic de novo variants of Gria4 have been linked to intellectual disability and social behavior deficits." (PMID 41150532, 2025). "In a recent exome sequencing study of individuals with intellectual disability, de novo heterozygous pathogenic variants in GRIA4 were found in five unrelated individuals with the condition." (PMID 31620175, 2019).
major depression (6 papers, 2009 to 2025). "Changes in GRIA4 expression have been associated with both depression and stress." (PMID 30287806, 2018).
epilepsy (5 papers, 2016 to 2023). A brain disorder characterized by episodes of abnormally increased neuronal discharge resulting in transient episodes of sensory or motor neurological dysfunction, or psychic dysfunction. "Variants in the GRIA4 gene have been associated with developmental disorders and different forms of epilepsy." (PMID 36901898, 2023). "These include the AMPAR subunit genes GRIA1, GRIA3, and GRIA4, causing an NDD spectrum including ID, loss of speech, epilepsy, gait abnormalities, and abnormal sleep patterns." (PMID 31300657, 2019).
absence seizures (4 papers, 2014 to 2024). "The further phenotypic difference between FeJ and B6J strains highlights the existence of additional genetic influences on Gria4 associated absence seizures." (PMID 25010494, 2014). "Each of three very closely-related C3H/He substrains has a similar level of spontaneous spike-wave discharges (SWD) - the distinctive electroencephalographic hallmark of absence seizures in human and in animal models - but only one substrain, C3H/HeJ (HeJ), carries a Gria4 mutation." (PMID 25010494, 2014). "Nevertheless, strain differences were noted for three different genes that cause absence seizures when mutated – Scn8a), Gabrg2 and Gria4, and for at least two the C3H strain generally worsens the absence seizure phenotype, compared with the relatively protective strain C57BL/6J (B6J)." (PMID 25010494, 2014). "For absence seizures caused by Gria4 mutation, the C3H strain has been a paradox." (PMID 25010494, 2014). "Further evidence that fast-feedforward disinhibition is a common mechanism that can lead to SWDs and absence seizures is provide by data from the GRIA4 knockout mouse, which lacks the GluA4 AMPA receptor subunit." (PMID 39337309, 2024). "For example, a recent study has identified a pathophysiological mechanism for the generation of absence seizures in the Gria4−/− mice model of absence epilepsy, for which the TRN receive reduced excitatory inputs from the direct Ctx-TRN neural projections." (PMID 28491031, 2017). "A few reports have associated GRIA4 variants with ID with or without seizures and studies on GRIA4 knockout mice suggest its involvement in the etiology of absence seizures." (PMID 35457207, 2022).
breast carcinoma (4 papers, 2010 to 2025). "GRIA4 hypermethylation has previously been reported to have prognostic value in breast cancer." (PMID 34922619, 2021).
colorectal cancer (4 papers, 2019 to 2023). A primary or metastatic malignant neoplasm that affects the colon or rectum. "When searching for other epigenetic biomarkers, gene GRIA4 (glutamate ionotropic receptor AMPA subunit 4) has great diagnostic potential in patients with colorectal cancer, although studies on its biological properties are quite limited." (PMID 37476382, 2023). "In colorectal cancer, a GRIA4 promotor region is hypermethylated to a greater extent compared to colon adenoma." (PMID 36901898, 2023). "The presence of methylated GRIA4 promoter was also observed in stool specimens, indicating its potential utility as a biomarker for the early detection of colorectal cancer from stool samples." (PMID 37476382, 2023).
glioma (3 papers, 2009 to 2023). A benign or malignant brain and spinal cord tumor that arises from glial cells (astrocytes, oligodendrocytes, ependymal cells). "The most notable lncRNA is LINC00599, which has DBSs in many NGS genes in most gliomas, including GABBR1, NRCAM, PTPRS, GLRB, GRIA4, GRIK3, and MAP2, and the most notable NGS gene is MAP2, which is associated with microtube assembly and regulated by multiple lncRNAs through the same DBS." (PMID 37693314, 2023).
myopia (3 papers, 2021 to 2024). "Interestingly, GRIA4 was also identified as a susceptibility locus for refractive error and myopia, implying additional roles in visual deterioration involved in domestication." (PMID 34009300, 2021).
Ataxia (2 papers, 2021 to 2022). Ataxia refers to impaired coordination of voluntary muscle movement. "Compared to the uninjured mice, we found that the mRNA expression levels of Gria3, Gria4, Grin2b, and Grin2c were markedly increased in DCN at day 7 post-SNC in non-ataxia control and ataxia mice." (PMID 36064798, 2022).
autism (2 papers, 2019 to 2022). Persistent deficits in social interaction and communication and interaction as well as a markedly restricted repertoire of activity and interest as well as repetitive patterns of behavior. "Importantly, de novo missense variants affecting the M3 channel gate or the M3-S2 linkers have been previously identified in several iGluR subunit genes (e.g., GRIA1, GRIA3, and GRIA4); phenotypes of these patients include ID, autism and epilepsy." (PMID 31300657, 2019).
Diabetes (2 papers, 2009 to 2013). "Diabetes had a greater effect on gene expression of NMDA and kainate receptor subunits than on the α-amino-3-hydroxy-5-methyl-4-isoxazole propionate (AMPA) receptor subunits, for which only GRIA4 significantly decreased after 12 weeks." (PMID 23878504, 2013). "Although there could be selective downregulation of GRIA4 and specific NMDA and kainate receptor subunits with no loss of ganglion cells, it is more likely that the ganglion cells expressing these receptors were lost by 12 weeks of diabetes." (PMID 23878504, 2013).
fibromyalgia (2 papers, 2024 to 2025). A chronic disorder of unknown etiology characterized by pain, stiffness, and tenderness in the muscles of neck, shoulders, back, hips, arms, and legs. "Gria4 in Cluster 3 has been proposed as a biomarker for developing new diagnostic methods for fibromyalgia." (PMID 41300284, 2025). "Other genes associated with fibromyalgia that regulate nociceptive and analgesic neuronal pathways are the TAAR1 receptor gene, the regulator of G protein signaling 4 gene (RGS4), the cannabinoid receptor 1 gene (CNR1), and the ionotropic glutamate receptor AMPA 4 gene (GRIA4)." (PMID 39062116, 2024).
medulloblastoma (2 papers, 2014 to 2020). A malignant, invasive embryonal neoplasm arising from the cerebellum. "Repression of glutamate receptor GRIA4, one of the top upregulated genes in our study, increases cell viability, proliferation, and migratory potential in rhabdomyosarcoma/medulloblastoma and multiple myeloma cells." (PMID 32260415, 2020).
migraine (2 papers, 2010 to 2016). "In this study we investigated the association of GRIA1, GRIA2, GRIA3 and GRIA4 genes that encode for the four subunits (GluR1-GluR4) of the alpha-amino-3-hydroxy-5-methyl-4-isoxazole-propionic acid (AMPA) ionotropic receptor and their variants to migraine with and without aura (MA and MO)." (PMID 20579352, 2010).
amnesia (1 paper, 2022). Pathologic partial or complete loss of the ability to recall past experiences ( AMNESIA, RETROGRADE) or to form new memories ( AMNESIA, ANTEROGRADE). "Internalization of Gria4 plays an important role in fine regulation of synaptic plasticity and is closely associated with long-duration inhibition and amnesia." (PMID 36432537, 2022).
autosomal recessive intellectual disability (1 paper, 2022). "It contains three genes GRM5, GRIK2, and GRIA4, and GluR6 is encoded by GRIK2 which is highly expressed in the brain and is associated with autosomal recessive intellectual disability." (PMID 36699455, 2022).
cardiomyopathies (1 paper, 2023). "In particular, Males Only DMRs selected by machine learning feature selection were able to distinguish CHD from non-CHD samples and frequently mapped to genes associated with CHDs or cardiomyopathies, including FUNDC1, ETV5, SYT9, CAMTA1, GRIA4, and IGF1R." (PMID 37803336, 2023).
cervical carcinoma (1 paper, 2021). A carcinoma arising from either the exocervical squamous epithelium or the endocervical glandular epithelium. "In addition, promoter DNA methylation levels (average beta values) of ALDH1A2, GATA4, GRIA4, and IRX4 were significantly elevated in primary cervical carcinoma as compared to normal tissues." (PMID 34745985, 2021).
cervical squamous cell carcinoma (1 paper, 2021). A squamous cell carcinoma arising from the cervical epithelium. "13.8% of 297 cervical squamous cell carcinoma cases revealed that genetic alterations in the five-gene signature with a low frequency of ALDH1A2 (1.3%), OSR2 (1%), GRIA4 (4%), GATA4 (1%), and IRX4 (7%)." (PMID 34745985, 2021).
cocaine addicts (1 paper, 2022). "Alcoholics and cocaine addicts show upregulation of three genes relative to controls: Gria4, Grik3, and Grm4." (PMID 36362437, 2022).
leukemia (1 paper, 2022). A malignant (clonal) hematologic disorder, involving hematopoietic stem cells and characterized by the presence of primitive or atypical myeloid or lymphoid cells in the bone marrow and the blood. "We identified 147 CRGs from 153 leukemia samples with only five observed in more than one sample (CEP164, DSCAML1, FXYD2, SIK3, and GRIA4)." (PMID 35945623, 2022).
mental disorder (1 paper, 2018). A disease that has its basis in the disruption of mental process. "Disease-level enrichment is more informative than GO level enrichment, in this instance: the disease enrichment analyses for the top genes or top coexpressed genes with GRIA4 shows that the significant enriched disease traits are mainly related to mental disorders." (PMID 30287806, 2018).
metastatic disease (1 paper, 2024). "Additionally, methylated GRIA4 has promising value as a marker of metastatic disease in CRC." (PMID 39385172, 2024).
Obesity (1 paper, 2022). Accumulation of substantial excess body fat. "Second, five proteins (CCL25, GRIA4, HBEGF, NPPA and RETN) were also considered because they have been reported to be associated with obesity." (PMID 35879730, 2022). "In addition, the proteins CCL25, GRIA4, HBEGF, NPPA and RETN, which are affected by RNAm-SNPs, have been reported to be related to obesity." (PMID 35879730, 2022).
Parkinson’s disease with dementia (1 paper, 2025). "Notably, several deregulated proteins in our study were further associated with dementia (Snca and Gria4)." (PMID 40545497, 2025).
Senile plaques (1 paper, 2011). Senile plaques are extracellular deposits of amyloid in the gray matter of the brain. "GRIA4 and GRIK1 are shown to be expressed in senile plaques (in temporal lobe) in microarray data but are not identified as expressed in the AD temporal lobe in the present RNA-Seq dataset." (PMID 21283692, 2011).